MITF (melanocyte inducing transcription factor)
Diseases named in the same sentence as MITF in open-access papers (continued):
Sharing a sentence is not in itself a finding about the gene and the disease.
melanoma (continued). "In addition, NFATc2, a transcription factor activated by oncogenic BRAF, was recently identified as a potent suppressor of MITF-PGC-1α in melanoma cells." (PMID 29629336, 2018). "Therefore, MITF or its target genes (e.g., tyrosinase) is clinically and cosmetically important for the treatment of melanoma and melanin-related skin diseases." (PMID 30249988, 2018). "MITF is one of the major transcription factors in melanocytes and melanoma cells." (PMID 29762513, 2018). "MITF plays an important pro-survival role in melanocytes and melanoma." (PMID 30513872, 2018). "Recently, MITF has been studied as a potential molecular target for melanoma therapy." (PMID 29755554, 2018). "Contrarily, MITF is downregulated in melanomas with acquired drug resistance." (PMID 29881716, 2018). "However, MITF is also reported as a driver of melanoma progression and long-term MITF depletion induces senescence in melanoma cells and/or promotes apoptosis." (PMID 29881716, 2018). "In addition, the extract of L. cuneata G. Don inhibited melanin synthesis in B16F10 murine melanoma cells by decreasing MITF, TRP1, and TRP2 protein levels and increasing the phosphorylated Erk and Akt." (PMID 30065832, 2018). "MITF also controls melanoma proliferation and invasiveness via regulation of Dia1." (PMID 30157785, 2018). "Moreover, multiple lines of evidence have shown that MITF plays an important role in melanoma biogenesis." (PMID 29903018, 2018). "Indeed, we found that co-culture with fibroblasts resulted in reduced expression of MITF and its target genes in melanoma cells." (PMID 29545604, 2018). "In addition, the induction of MITF and Tyrosinase expression paralleled by miR-221&222 down-modulation, showed the influence of OA also on melanoma differentiation." (PMID 29484133, 2018). "Although there is no direct nor mechanistic evidence of the MITF-CRYAB transcriptional axis in other cancer types, in melanoma both MITF and CRYAB expression are upregulated by BRAF/MEK-inhibitor treatments, suggesting that this regulation can go beyond both PCa scenario." (PMID 30310055, 2018). "Thus, targeting this slow-cycling subpopulation by modulating MITF levels can be a potential strategy to overcome drug resistance in melanoma." (PMID 29881716, 2018). "In addition it was recently reported that MITF represses miR-221&222 promoter and in turn its absence in advanced melanomas contributes to miR-221&222 up-regulation, thus effectively initiating melanoma invasion." (PMID 29484133, 2018). "Thus, for a high expression of SC marker SOX2, which is critical for forming the tumour‐initiating cells in melanoma 34, low‐MITF level is required." (PMID 29369499, 2018). "For instance, RNA-seq analysis of human melanoma COLO829 cells transfected with MITF short hairpin RNA (shRNA) demonstrates an up-regulation of over 17 of the same 55 innate immune DEGs identified in Mitfmi-vga9/+ McSCs, including Ifih1, Ifit3, Irf7, Parp9, and Stat1 (GSE50686)." (PMID 29723194, 2018). "Furthermore, Wnt signaling contributes to the stabilization of MITF, thereby sustaining this pathway in melanocytes and melanoma cells." (PMID 30197759, 2018).
melanoma (continued). "Considering the dynamic expression of MITF in response to changing microenvironmental conditions at various phases of melanomagenesis, MITF levels can be considered as a predictive marker for a suitable therapy regimen for treating a particular melanoma phase." (PMID 29881716, 2018). "Until now, there are no data regarding PAX6 role in melanoma progression, however, it has been strongly linked to a feed-forward regulatory loop with MITF during the onset of melanogenesis." (PMID 29855470, 2018). "In melanoma, MITF acts as a molecular switch that determines whether the cell will differentiate, proliferate, or become quiescent with increased migratory behavior." (PMID 29881716, 2018). "Furthermore, IPA protein-protein interaction (PPI) analysis for co-module #12 showed that melanoma-related transcription factors, such as MITF, PAX3, SOX8, and SOX10, formed a sub-network." (PMID 29950679, 2018). "BRAF mutation and CDKN2A inactivation have been found associated with MITF amplification in melanoma cell lines, but such a correlation was not confirmed in our series." (PMID 29492214, 2018). "The antiapoptotic role of MITF in melanomas is clearly established." (PMID 29369499, 2018). "However, some concern remains how the antiapoptotic signals are sustained in melanoma cell lines in which MITF expression is very low or in low‐MITF (and more invasive) areas of tumours." (PMID 29369499, 2018). "Although a correlation between BRAF mutation and MITF activation was detected, they did not completely overlap in melanoma cells." (PMID 29950679, 2018). "As CD271 shows a role opposite to that of MITF, one possibility could be to treat melanoma with drugs inducing MITF14 and at the same time blocking CD271 upregulation or function in order to prevent phenotype switching." (PMID 29215016, 2017). "The melanocytic lineage-specific and MITF-regulated miR-211 is invariably down-regulated and frequently lost or epigenetically silenced in melanoma samples (a decrease in its expression levels is enough to distinguish nevi from melanomas)." (PMID 28445987, 2017). "Likewise, when comparing MITF-m transcripts with Breslow index, the significance was observed only for thin melanoma (≤ 1.5, p = 0.021), which is often related to the early stages of the disease." (PMID 29156734, 2017). "For melanoma cell lines, the preeminent factors are the presence of the most significantly mutated genes (BRAF, NRAS, NF1, or triple wild type) and proliferative or invasive behavior (MITF/AXL expression ratio)." (PMID 29383127, 2017). "MITF is detected in ~70% of treatment naive melanomas, which have been classified as MITF‐high." (PMID 28606996, 2017). "Similarly, the SWI/SNF ATPases promote MITF-driventranscription in melanoma cells and further add to the increasedtranscriptional activity of MITF target genes by stimulating increasedexpression of MITF itself." (PMID 28521512, 2017). "Notably, we determined that wogonin inhibited MITF expression and melanosome transport in human melanoma MM–AN cells." (PMID 28182699, 2017). "The proliferative signature was associated with high expression of MITF, while the invasive melanoma cells exhibited little or no expression of MITF." (PMID 28883623, 2017). "MITF induction in melanoma has been proposed as a possible therapy for melanoma because, when elevated in cancer cells, it triggers differentiation and sensitizes melanoma to TMECG, a drug inducing apoptosis." (PMID 29215016, 2017). "Furthermore, melanoma cells with low MITF levels that were transfected with vectors for expression of MITF and OCT4 showed a significant decrease in TRPM1 mRNA levels compared to the control." (PMID 29044103, 2017). "Finally, we found that modulation of ILEI affects invasive potential in MITF-low invasive melanoma cell lines." (PMID 28545079, 2017).
melanoma (continued). "Thus, in summary, in melanoma cells, it appears that an altered glucose metabolism has seized control over the expression of MITF, thereby rendering these cells dependent on glucose to drive proliferation." (PMID 28380427, 2017). "Taken together, the presented data reveal that the inhibition of NAT10 by small molecules or genetic silencing suppresses melanin synthesis and melanoma growth by decreasing the expression of MITF and its target genes related to pigmentation and cell proliferation." (PMID 28880216, 2017). "We therefore tested whether glucose restriction might limit melanoma cell proliferation by affecting MITF expression." (PMID 28380427, 2017). "In melanoma cells, MITF regulates the expression of PGC1α, a marker of an oxidative phenotype." (PMID 29137417, 2017). "MITF promotes glycodelin expression of melanoma cells and the crosstalk between MITF and glycodelin may regulate melanoma progression." (PMID 29238349, 2017). "Indeed, glucose restriction resulted in a strong up-regulation of ATF4 in melanoma cells, and this correlated with reduced MITF expression." (PMID 28380427, 2017). "Thus, heterogeneity in MITF expression not only characterizes distinct melanoma phenotypes, but also allows for the creation of a mini‐community in which cells with different properties influence one another's drug response profiles via paracrine signals." (PMID 28694322, 2017). "Interestingly, MITF drives metabolic reprogramming of melanoma cells towards mitochondrial metabolism by promoting the transcription of several genes involved in OXPHOS." (PMID 28036292, 2017). "Together with recent reports suggesting that fasting cycles can significantly affect tumour growth and responses to chemotherapy it will be of upmost interest to determine the role of ATF4 in all these processes and the interplay between ATF4 and the master regulator of melanoma biology MITF." (PMID 28380427, 2017). "In addition, we sought to identify melanoma cell lines that are better models of their tumour counterparts while accounting for MITF or AXL enriched transcriptional states." (PMID 28060736, 2017). "Additionally, circulating tumor cell (CTC) studies have shown that melanoma CTCs express MITF, suggesting MITF-expressing cells can be actively invasive." (PMID 28545079, 2017). "Interestingly, OCT4 and MITF are inversely correlated in different melanoma cell lines and seem to be uniquely expressed in skin cutaneous melanoma." (PMID 29044103, 2017). "Indeed, it has been reported that the downregulation of MITF expression by tea catechins was responsible for a reduction of melanin synthesis in mouse and human melanoma." (PMID 28825660, 2017). "In addition, MITF has been reported as an amplified oncogene in human melanomas and displays functional roles in transcriptional gene expression related to survival, proliferation, cell cycle progression, and chemoresistance." (PMID 28880216, 2017). "However, ATF4 only bound to the MITF promoter when glucose levels in melanoma cells were restricted." (PMID 28380427, 2017). "In addition, they suggest that TFAP2A activity, like MITF activity, has the potential to modulate the phenotype of melanoma cells." (PMID 28249010, 2017). "Therefore, like CRD-BP, MITF represents a good target for anti-cancer therapy particularly in the treatment of melanoma." (PMID 28182633, 2017). "In melanoma, MITF is both a pro-survival and a differentiating factor." (PMID 28036292, 2017). "Moreover, in human primary melanoma cells, a high level of VEGF-C and a low level of MITF (microphtalmia-associated transcription factor) correlate in a p38-dependent manner with an increase risk of metastasis associated with lymphangiogenesis." (PMID 28903453, 2017).
melanoma (continued). "Global pathway analysis showed significantly similar transcriptional alterations following MITF knockdown in all melanoma cell lines as indicated by either the predicted upstream molecules or functional pathway annotation that would elicit the observed gene expression changes." (PMID 28883623, 2017). "The fact that MITF expression from an ectopic promoter could overcome glucose-dependence in melanoma cells, suggested that glucose regulates MITF at the transcriptional level." (PMID 28380427, 2017). "In summary, we could confirm our computational predictions, i.e. SOX5 is inducing and SOX10 is repressing MITF expression in the observed melanoma cells." (PMID 26927636, 2016). "Surprisingly, AURKA inhibition induced MITF expression in all tested melanoma cell lines." (PMID 26962685, 2016). "We next asked whether Lunasin treatment can modulate MITF expression in CICs and thereby, trigger a phenotypic switch in CICs that will ultimately drive the Lunasin-treated melanoma CICs towards differentiation." (PMID 27566591, 2016). "Indeed, both transcription factors were capable to explain the differences in MITF expression levels when trained with a dataset of cells from different tumors and applied to a different dataset, i.e. a dataset of melanoma cell lines." (PMID 26927636, 2016). "An increase in the expression of MITF was previously reported to contribute to tumor progression and resistance to BRAFi in a subset of melanomas, whereas low levels of MITF expression were shown to predict intrinsic MAPKi resistance, highlighting the dual function of this factor." (PMID 27596438, 2016). "We observed a decrease in MITF levels after treatment in two out of eight patients (some clones of patient 1), while these levels were maintained (patient 2) or increased (patients 3 and 4) in most melanoma relapse samples after vemurafenib treatment." (PMID 27596438, 2016). "Interestingly, the prediction of Breslow thickness using all of the investigated regulators (SOX5, SOX10, and MITF) showed good prediction performance only for thin melanoma tumors (<1 mm) and was rather poor for thick melanomas." (PMID 26927636, 2016). "Furthermore, to obtain a more objective and quantitative measurement of micrometastasis, we assessed the gene expression of melanoma-related genes (MITF, MLANA, TYR and TYRP) in RNA extracts from lungs and livers of experimental groups." (PMID 27120788, 2016). "Indeed, primary cross-resistance to BRAF and MEK inhibitors has been documented in a subset of melanomas, where it is related to the MITF profile, and in cell lines." (PMID 26678033, 2016). "Waardenburg syndrome 2A (WS2A) [MIM:193510], Waardenburg syndrome 2, with ocular albinism, autosomal recessive (WS2-OA) [MIM:103470], Tietz syndrome (TIETZS) [MIM:103500], Melanoma, cutaneous malignant 8 (CMM8) [MIM:614456] are all caused by mutations in MITF [UniProt: O75030]." (PMID 26868667, 2016). "Since loss of MITF is also accompanied by increased invasiveness, it supports previous findings that a high level of AXL expression is associated with a pro-invasive phenotype in melanoma." (PMID 27102439, 2016). "Starting from comparative transcriptomics analysis using data from cells originating from nine different tumors and a melanoma cell dataset, we predicted the transcriptional regulators of MITF employing ChIP binding information from a comprehensive set of databases." (PMID 26927636, 2016). "Furthermore, we wanted to confirm computationally that SOX5 and SOX10 are regulators of MITF expression in melanoma cells and thus analyzed a dataset of melanoma cells only." (PMID 26927636, 2016). "Moreover, an independent study utilized RNA-seq analysis to identify factors that protect MITF low melanoma cells from MAPK inhibition and identified AXL as a key RTK upregulated during resistance." (PMID 27834845, 2016).
melanoma (continued). "According to the rheostat model proposed for MITF in melanoma cells, increasing levels of MITF are associated not only with a more differentiated phenotype with less cell proliferation, as previously shown, but also with noninvasive properties." (PMID 27399772, 2016). "A previous study found that PMEL was an MITF target gene in melanocytes and melanoma, with its mRNA levels being enhanced upon transfer of wt MITF and blocked by a dominant negative form of MITF, which indicated that the expression level of MITF was necessary for the PMEL gene transcription." (PMID 27690000, 2016). "MITF, another down regulated gene in our data set functions as a ‘rheostat model’ controlling phenotypic switches between proliferative, differentiated and tumorigenic/invasive phenotypes as shown in malignant melanoma." (PMID 27280700, 2016). "MITF (microphthalmia-associated transcription factor) is a frequently amplified lineage-specific oncogene in human melanoma, whose role in intrinsic drug resistance has not been systematically investigated." (PMID 26962685, 2016). "Besides SOX10, we identified SOX5 regulating MITF in human melanoma cells and validated its inhibitory effect experimentally by functional and reporter assays." (PMID 26927636, 2016). "We analyzed melanomas from 11 patients undergoing treatment with vemurafenib or a dabrafenib/trametinib combination, and found that, within the first 2 weeks of treatment, MITF expression was upregulated in 9 of 11 patients." (PMID 26977879, 2016). "Using our established regression model (MILP model) and the defined activity, we found the transcription factors SOX5 and SOX10 with which the model could predict best the gene expression values of MITF in various melanoma cell lines." (PMID 26927636, 2016). "It has been established that increasing cellular levels of MITF are responsible for a melanoma phenotype switching from a dormant state with low levels of MITF to a proliferative state with intermediate MITF levels and finally to a differentiated phenotype with higher MITF levels." (PMID 27399772, 2016). "Wellbrock and coworkers proposed that a low basal MITF level could be important for the survival of melanoma cells and also for their proliferation through regulation of cyclin-dependent kinase 2 (CDK2) and B-cell CLL/lymphoma 2 (BCL2)." (PMID 26927636, 2016). "Thus, we performed functional assays to validate our in silico predictions in human melanoma cells and investigated the expression signatures of MITF, SOX5 and SOX10 in respect to clinically relevant parameters." (PMID 26927636, 2016). "One report showed that SUMOylation-defective MITF germline mutation predisposes carriers to melanoma and renal carcinoma, but, so far, there is no report on a clear role of SENP1 in renal cell carcinoma." (PMID 27741516, 2016). "In addition to low levels of MITF, different markers, including ABCB5 and JARID1B, have been associated with the generation of melanoma‐initiating cells." (PMID 27596438, 2016). "Quantitative analysis of β-catenin protein as well as its functional activation, measured by quantification of mRNA levels of the ubiquitously target gene AXIN2 and of the melanocyte specific marker MITF showed a heterogeneous level of WNT pathway activation in melanoma cells." (PMID 27175588, 2016). "This further emphasizes the relevance of the BRAF/MITF connection for melanoma development." (PMID 27200346, 2016). "Notably, these results contribute to the explanation of the antiproliferative effect of Lebein on melanoma cells, increasing MITF levels through inhibition of ERK phosphorylation." (PMID 27399772, 2016). "In line with this, melanoma subpopulations have been shown to harbor specific gene expression programs, whereby “proliferative” melanoma cells display MITFhigh, SOX10high, and PAX3high, in line with the reported function of MITF in driving endosomal biosynthesis and Wnt-mediated proliferation." (PMID 27896217, 2016).